RUSF1 (RUS family member 1)
Synonyms: C16orf58; FLJ13868; RUS
Tractability: Antibody: UniProt predicts a signal peptide or a membrane-spanning region. PROTAC: ubiquitination databases record sites on it.
Gene: Protein-coding gene on chromosome 16 (31,489,471 to 31,509,309, reverse strand). Ensembl gene ENSG00000140688.
Subcellular location: Membrane
Subcellular location (Human Protein Atlas): Golgi apparatus; Nucleoli; Vesicles; Cytosol; Nucleoplasm
Gene Ontology:
Molecular function: protein binding
Cellular component: membrane
Genetic constraint (gnomAD): Loss-of-function variants: 58 observed, 57.25 expected, observed/expected ratio (o/e) 1.01, 90% interval 0.82 to 1.26. The upper end of that interval is the gene's LOEUF score, 1.26, which puts it in group 5 of 6, group 1 being the genes least tolerant of losing a copy. Missense variants: 652 observed, 577.69 expected, observed/expected ratio (o/e) 1.13, 90% interval 1.06 to 1.2. Synonymous variants: 274 observed, 241.05 expected, observed/expected ratio (o/e) 1.14, 90% interval 1.03 to 1.26.
Homologues: Orthologues: chimpanzee RUSF1 (99% identical), macaque RUSF1 (97% identical), dog RUSF1 (85% identical), rabbit RUSF1 (85% identical), pig RUSF1 (83% identical), mouse Rusf1 (81% identical), guinea pig RUSF1 (79% identical), rat Rusf1 (79% identical), zebrafish rusf1 (45% identical), tropical clawed frog rusf1 (44% identical), Drosophila melanogaster CG10338 (35% identical).
Diseases named in the same sentence as RUSF1 in open-access papers:
RUSF1 is named in the same sentence as 1 disease in open-access papers, as found by Europe PMC text mining. Sharing a sentence is not in itself a finding about the gene and the disease.
RUSF1 shares sentences with these, for which no sentence is quoted: cancer (1 paper).